CD4 (CD4 molecule)
Diseases named in the same sentence as CD4 in open-access papers (continued):
Sharing a sentence is not in itself a finding about the gene and the disease.
aortitis (3 papers, 2019 to 2022). Inflammation of the aorta. "Additionally, G-CSF-induced autoimmune reactions mediated via IL-6 between Th17 cells and CD4+ T cells is also thought to result in aortitis, aneurysm or dissection." (PMID 33122662, 2020). "We found that CD11c+ dendritic cells (DCs), Gr1+ neutrophils, and GL3+ γδT cells—but not CD4+ T cells, CD8+ T cells or Mac2+ macrophages—were IL-1Ra–producing EGFP+ cells in the lesions of aortitis (and data not shown)." (PMID 31745167, 2019).
asbestosis (3 papers, 2021 to 2023). A lung disorder caused by inhalation of asbestos fibers. "Our study found that decreased PD-1 expression on CD4+ or CD8+ T cells in peripheral blood (PB) was positively correlated with the disease severity of asbestosis." (PMID 34022844, 2021). "More importantly, the proportions of CD4+ PD-1+ T cells and CD8+ PD-1+ T cells in patients with asbestosis were positively correlated with the percentage of FVC predicted." (PMID 34022844, 2021). "Moreover, the proportions of PD-1+ CD4+ T cells and PD-1+ CD8+ T cells in patients with asbestosis were positively correlated with the percentage of forced vital capacity predicted." (PMID 34022844, 2021).
ascariasis (3 papers, 2015 to 2021). An infection that is caused by the roundworm Ascaris lumbricoides, many cases of which remain asymptomatic. "It was found that, in mothers with ascariasis, there is an in utero sensitization of newborns to Ascaris lumbricoides, with a greater frequency of CD4+ T cells producing IFN-γ and IL-4 in CB from newborns of infected mothers, showing that the immunological effects of infection develop in the fetus." (PMID 33668787, 2021). "Albendazole treatment during Ascaris lumbricoides infection might decrease worm load leading to a reduction in IL-10 production, which ultimately improved cellular immunity and CD4+T cell counts." (PMID 28761478, 2017). "The study showed that treatment of ascariasis had a significant effect on CD4+ T-cell count increase in the treated Pre-ART Ascaris lumbricoides/HIV co-infected individuals; whereas the same positive effect was not evident for other intestinal helminth parasites detected in the study." (PMID 26415705, 2015).
autism spectrum disorder (3 papers, 2012 to 2025). A spectrum of developmental disorders that includes autism, and Asperger syndrome. "HLA DR*04, which was linked to low (and narrow) CD4 T-cell responses to HIV is also reportedly associated with low CD4 T-cell responses to mitogens in Autism Spectrum Disorder." (PMID 22693541, 2012). "(2025) demonstrated that maternal vitamin D promotes glycolytic reprogramming of offspring CD4+ T cells, enhancing immune tolerance and reducing inflammation, with downstream effects on reducing autism spectrum disorder (ASD)‐like behaviors." (PMID 41273001, 2025).
autoimmune peripheral neuropathy (3 papers, 2015 to 2024). "IL-21–expressing CD4+ T cells, as crucial pathogenic immune cell types, characterize mouse models of autoimmune peripheral neuropathies similar to chronic inflammatory demyelinating polyneuropathy and Guillain-Barré syndrome." (PMID 39087473, 2024). "Thus, the development of autoimmune peripheral neuropathy in NOD.AireGW/ mice was associated with IL-21 upregulation in peripheral nerve CD4+ T cells." (PMID 39087473, 2024). "In an adoptive transfer model of autoimmune neuropathy, we found that 79-6 treatment was accompanied by a decrease in the frequency of nerve-infiltrating Tph (CD4+ICOS+CXCR5–PD-1+CXCR6+) cells compared with vehicle treatment." (PMID 39087473, 2024). "Because experimental allergic neuritis (EAN), the most used animal model for the study of autoimmune peripheral neuropathy, is driven mainly by CD4+ T cells, CD4+ T cells have been the main area of research for decades." (PMID 26528293, 2015). "Clonal expansion of CD4+ T cells in the NOD.AireGW/ model of autoimmune peripheral neuropathy may reflect escape of PNS-reactive clones from the Aire-deficient thymus." (PMID 39087473, 2024). "Different from EAN where CD4+ T cells are the main culprits in mediating neuropathy, L31 mice provide a unique opportunity to investigate the involvement of CD8+ T cells in autoimmune peripheral neuropathy." (PMID 26528293, 2015).
bartonellosis (3 papers, 2019 to 2022). An infectious disease produced by bacteria of the genus Bartonella. "Furthermore, an inverted CD4+/CD8+ ratio should be proposed as a novel marker for bartonellosis." (PMID 36425135, 2022). "infection also showed a significant, inverted CD4+/CD8+ ratio, which may be used as a novel marker in bartonellosis." (PMID 36425135, 2022).
benign ovarian tumor (3 papers, 2020 to 2023). "It was found that the positive expression rates of Glut1, HIF-1α, and Ki67 in CD4+ Treg cells of OC were significantly higher than that in benign ovarian tumor and HC, and also significantly higher than that in CD4+ Teffs of OC." (PMID 33414414, 2021).
biliary tract cancer (3 papers, 2022 to 2025). "Specifically, it highlights the association of B cells expressing CD20 and BAFF-R with reduced biliary tract cancer risk, while CD4RA+CD4+ T cells exhibit anti-tumor effects in biliary tract cancer." (PMID 39050844, 2024). "This underscores the association between CD4-expressing regulatory T cells and biliary tract cancer." (PMID 39050844, 2024). "This study implies an association between CD4RA+CD4+ T cells and a decreased risk of biliary tract cancer." (PMID 39050844, 2024). "In the mature stage of T cells, only one immunophenotype of T-cells in the maturation stage was negatively associated with risk of biliary tract cancer, CD4RA on TD CD4+, which was protective against a reduced risk of biliary tract cancer, as detected by an OR<1 (OR=0.95, 95% CI=0.90–1.00, P=0.034)." (PMID 39050844, 2024). "Studies have found that patients with biliary tract cancer who have intraepithelial tumor-infiltrating CD4+, CD8+, and Foxp3+ T lymphocytes exhibit significantly longer overall survival." (PMID 39050844, 2024). "Within the epithelial tumor infiltration in biliary tract cancer, CD4+ and CD8+ T lymphocytes exhibit synergistic anti-tumor effects." (PMID 39050844, 2024). "A follow-up investigation involving 306 individuals diagnosed with biliary tract cancers demonstrated a positive correlation between longer overall survival (OS) and increased tumor infiltration of total CD4+ tumor-infiltrating lymphocytes." (PMID 39050844, 2024). "The density of Foxp3- CD4+ helper T cells in the tumor margin rather than the tumor center and stroma has previously shown the best capacity for predicting the treatment response in biliary tract cancer patients, and the tumor margin may be the main site of the immune response in these cases." (PMID 36237314, 2022).
Blastic plasmacytoid dendritic cell neoplasm (3 papers, 2013 to 2020). "A CD4+CD56+ hematological malignancy was classified as blastic plasmacytoid dendritic cell neoplasm (BPDCN) due to its expression of characteristic molecules of pDCs." (PMID 25779340, 2015). "CD4+CD56+ hematologic malignancy with primary cutaneous presentation has been well documented and is proposed as the malignant counterpart of pDC precursors and was named as blastic plasmacytoid dendritic cell neoplasm (BPDCN)." (PMID 25779340, 2015).
blastomycosis (3 papers, 2010 to 2023). Blastomycosis is a rare infection that may develop when people inhale a fungus called Blastomyces dermatitidis, a fungus that is found in moist soil, particularly where there is rotting vegetation. "The final diagnosis was that of Idiopathic CD4+ Lymphocytopenia with disseminated Blastomycosis involving adrenal gland, vocal cord and probable lung and brain, in an HIV negative non-immunosuppressed patient." (PMID 20806085, 2010).
Blindness (3 papers, 2016 to 2019). Blindness is the condition of lacking visual perception defined as a profound reduction in visual perception. "Systematic screening of HIV patients with CD4 counts below 100 cells/μl should be carried out to detect disease at an early stage, when blindness can still be prevented." (PMID 27788232, 2016). "In the CD4 cells of our patients, we found that SPPL2B expression was common to both those with raised WCC and jaw claudication whilst MATR3 was associated with raised WCC and long-term monocular blindness." (PMID 30037347, 2018).
bone tumors (3 papers, 2021 to 2024). "The possible changes in the shift of T helper cells and the pattern of CD4 + and CD8 + T cells in patients with different primary bone tumors were evaluated by determining the percentages of CD4 + and CD8 + T cells using flow cytometry." (PMID 37993664, 2023). "In the case of the OST of the jaws, it has been suggested that the absent or weak infiltration of CD4 and CD8 T cells was one of the possible explanations for the aggressiveness of this specific type of bone tumor." (PMID 34885185, 2021).
brain hemorrhage (3 papers, 2023). "In addition, FUS-induced cavitation of microbubbles still poses a risk of tissue injury and inflammatory response has been observed (e.g. infiltration, activation of CD4+ and CD8+ T cells, and cytotoxicity of Cytotoxic T lymphocytes), and brain hemorrhage." (PMID 36533878, 2023).
bronchopneumonia (3 papers, 2016 to 2024). Acute inflammation of the walls of the terminal bronchioles that spreads into the peribronchial alveoli and alveolar ducts. "After IAV infection, children with bronchopneumonia (BPI) have higher counts of BA, Pltand CD8+ T cell and percentage of Pct, T cells and CD4+ T cells than those with URT infections (UI)." (PMID 39949573, 2024).
cardiac arrest (3 papers, 2018 to 2023). Cessation of breathing and/or cardiac function. "Hence, the results from this studysuggest the possibility that quantitation of CD4+CD25+Treg cells in the blood can beexploited as a potential clinical biomarker for outcome prognosesin cardiac arrest patients." (PMID 37967214, 2023).
carditis (3 papers, 2012 to 2016). "Nevertheless, CCL2 has been demonstrated to enhance migration of T cells across B. burgdorferi-stimulated HUVEC, and B. burgdorferi -specific CD4+ T cells were shown to play important roles in the severity of murine Lyme arthritis and carditis." (PMID 23024745, 2012). "This led to contrasting reports for the role of CD4+ T cells in Lyme arthritis and carditis." (PMID 27857714, 2016).
Cerebral atrophy (3 papers, 2010 to 2025). Atrophy (wasting, decrease in size of cells or tissue) affecting the cerebrum. "In line with this hypothesis, one study observed a decreased rate of cerebral atrophy in PLWH who had improving CD4 count trajectories." (PMID 38856821, 2024).
cerebral oedema (3 papers, 2014 to 2024). "Of significance is the finding on multivariate analysis that a CD4 count <50 is associated with increased risk for SOL/cerebral oedema." (PMID 29568583, 2015). "However, after multivariate analysis only, a CD4 count <50 was associated with an increased risk for SOL/cerebral oedema." (PMID 29568583, 2015). "Multivariate analysis showed a CD4 count <50 (p = 0.033) to be a statistically significant predictor of patients with SOL and cerebral oedema." (PMID 29568583, 2015).
Chagas cardiomyopathy (3 papers, 2022 to 2025). A disease of the cardiac muscle developed subsequent to the initial protozoan infection by trypanosoma cruzi. "Our results demonstrate an expansion in activated CD4+ T cells and a decrease in a functional subset of regulatory T cells associated with the onset of Chagas cardiomyopathy, suggesting their role in the establishment of cardiac lesions and as potential biomarkers for disease aggravation." (PMID 36447264, 2022). "Cells with cytotoxic CD4+ T cell phenotype predominate in the cardiac tissue of infected mice and are at higher frequencies in patients with Chagas cardiomyopathy (CC)." (PMID 35670567, 2022).
childhood asthma (3 papers, 2010 to 2024). "Relationship of CD4+/IL-13+ T cells with disease activity suggests that this lymphocyte subset may have a prominent role in childhood asthma." (PMID 21197090, 2010). "The correlation analysis displayed that the mRNA level of c-CBL in CD4 + T cells was negatively related with the percentage of Th2 cells in blood of asthmatic and control children, suggested that the decreased expression of c-CBL may be involved in development of childhood asthma." (PMID 39342146, 2024). "Furthermore, IL-2 can modulate the differentiation of CD4+ T helper (Th) cell subsets, including T-helper 1 (Th1), T-helper 2 (Th2), T-helper 17 (Th17), and regulatory T (Treg) cells, the key pathways in allergic and non-allergic inflammation and childhood asthma." (PMID 33810791, 2021).
cholangitis (3 papers, 2018 to 2026). An acute or chronic inflammatory process affecting the biliary tract. "Overall, these data support the notion that testosterone reduces the activation of human CD4+ T cells, which is in line with our previous findings on the suppressive effects of testosterone on CD4+ T cells in a mouse model of cholangitis." (PMID 40260919, 2025).
choroiditis (3 papers, 2009 to 2025). An inflammatory process that affects the choroid. "However, ocular tumor growth also generated immunosuppressive CD8+ Treg that inhibited CD4+ T cell mediated DTH responses to tumor Ags." (PMID 23060881, 2012). "As Ad5E1 tumors do not express MHC Class II these data suggest a model in which CD4+ T cells infiltrating ocular tumors express IFNγ only after engaging tumor Ags complexed with MHC Class II that are presented by ocular APC, most probably intratumoral macrophages." (PMID 23060881, 2012). "While these data suggested that DTH responses were critical for ocular tumor elimination, additional experiments showed that administration of anti-CD4 antibodies, which abrogated DTH responses measured in the footpad, did not prevent rejection of intraocular P91 tumors." (PMID 23060881, 2012). "The median CD4 count in cases of tubercular choroiditis was 29 cells/μL." (PMID 19775470, 2009). "Progressive growth of tumors in the a.c. fails to generate CD4+ T cell dependent DTH responses to ocular tumor Ags, and restoration of these DTH responses has been associated with rejection of intraocular tumors." (PMID 23060881, 2012). "However, CD4+ T cell infiltration of ocular tumors does not appear to be compromised as Ad5E1 tumors are spontaneously rejected when placed in the a.c. by a process that requires CD4+ T cells, macrophages, and IFNγ." (PMID 23060881, 2012). "However, as restoration of CD4+ T cell responses to tumor Ags does not assure ocular tumor elimination the contribution of CD8+ Treg in ocular tumor progression remains unclear." (PMID 23060881, 2012).
chromoblastomycosis (3 papers, 2014 to 2026). "Previous studies have shown that recruitment of CD4+, although not CD8+, T cell-mediated immune response contributes to the host defense against experimental chromoblastomycosis." (PMID 25490199, 2014).
cocaine abuse (3 papers, 2008 to 2021). Disorders related or resulting from use of cocaine. "This conceivably could account for the deleterious effects of cocaine abuse on accelerated CD4+ T cell apoptosis in HIV-1 patients, because increased viral integration has been proposed to induce CD4+ T cell apoptosis." (PMID 26539167, 2015).
collagenous colitis (3 papers, 2014 to 2025). A type of microscopic colitis of unknown etiology. "However, CD4+ T‐lymphocytes predominated in two cases of ICI‐associated collagenous colitis." (PMID 40769948, 2025). "Our finding of increased numbers of mucosal CD4+ T helper cells in untreated active collagenous colitis patients is in line with a previous study." (PMID 36591297, 2022). "In another study, that included a mixed cohort of treated/untreated collagenous colitis patients, the lamina propria CD4+ percentages were equal to healthy controls but showed signs of increased activation in collagenous colitis." (PMID 36591297, 2022). "In untreated active collagenous colitis, the lymphocyte composition of the colonic mucosa showed increased T cells, with an increase of both CD8+ cytotoxic and CD4+ helper T cells." (PMID 36591297, 2022). "In the mucosa of budesonide refractory collagenous colitis, we found higher numbers of CD8+ and CD4+ T cells and MAIT cells when compared to untreated active collagenous colitis patients." (PMID 36591297, 2022). "We found that most of the cell populations studied were increased in refractory patients and different T cell subsets (CD4+, CD8+ and MAIT) constituted the vast majority of mucosal lymphocytes in refractory collagenous colitis." (PMID 36591297, 2022). "We confirm previous findings that peripheral CD4+ T cells do not differ in active collagenous colitis or during remission." (PMID 36591297, 2022).
colonic disease (3 papers, 2016 to 2021). "Although pTreg cell generation was not addressed in such condition, this phenomenon was probably insufficient to mediate intestinal homeostasis, as mice receiving low and high doses of colitogenic CD4+ T cells displayed equivalent colon disease." (PMID 27353032, 2016). "As diseased colonic tissue, but not the unaffected duodenum, contained mainly CD4+ T cells with a prominent IFNγ-signature, we hypothesize that local microbial stimulation may have initiated colonic disease." (PMID 34226674, 2021). "However, it has never been determined whether, in the presence of physiological proportions of non-T cells in the inoculum, increased numbers of naïve CD4+ T cells could generate enough pTreg to influence the outcome of colon disease." (PMID 27353032, 2016).
complex regional pain syndrome (3 papers, 2020). A chronic pain syndrome characterized by a disproportionate spontaneous or stimulus-induced pain, accompanied by a variably mixed myriad of autonomic and motor disorders including symptoms such as swelling, allodynia, skin blood supply and trophic disturbances. "The increase in central memory CD4+ T-cells and memory Tregs is consistent with the findings in a recent report that used mass cytometry to investigate blood immune subsets in complex regional pain syndrome, another condition in which inflammation persists long after the original injury." (PMID 32793203, 2020). "In a study of 14 patients with complex regional pain syndrome (CRPS) and 14 controls, Russo and colleagues used mass cytometry to identify an expansion of both CD4+ and CD8+ memory T lymphocytes in patients compared to controls." (PMID 32153361, 2020).
complication (3 papers, 2016 to 2025). Any disease or disorder that occurs during the course of, or because of, another disease, treatment, or procedure. "Lei and colleagues found that LT recipients with biliary complications experienced a decrease in CD4 + T cells, naïve T cells, and stem cell memory T cells." (PMID 39885500, 2025). "Of the participants showing HIV-related ocular complications, 50 % (24/48) were found among participants with CD4 values less than or equal to 200 cells/μL; this was followed by 29 % (14/48) in the participants with CD4 counts between 201 and 500 cells/μL." (PMID 27487853, 2016). "Majority of participants 50 % (24/48) in this study diagnosed with ocular complications had CD4+ T cell counts less than 200 cells/μL; this indicates that a CD4+ T –cell count of less than 200 cells/μL predisposes HIV patients much more to the development of ocular complications." (PMID 27487853, 2016).